BUB1 (BUB1 mitotic checkpoint serine/threonine kinase)
Description:
Serine/threonine-protein kinase that performs 2 crucial functions during mitosis: it is essential for spindle-assembly checkpoint signaling and for correct chromosome alignment. Has a key role in the assembly of checkpoint proteins at the kinetochore, being required for the subsequent localization of CENPF, BUB1B, CENPE and MAD2L1. Required for the kinetochore localization of PLK1. Required for centromeric enrichment of AUKRB in prometaphase. Plays an important role in defining SGO1 localization and thereby affects sister chromatid cohesion. Promotes the centromeric localization of TOP2A. Acts as a substrate for anaphase-promoting complex or cyclosome (APC/C) in complex with its activator CDH1 (APC/C-Cdh1). Necessary for ensuring proper chromosome segregation and binding to BUB3 is essential for this function. Can regulate chromosome segregation in a kinetochore-independent manner. Can phosphorylate BUB3. The BUB1-BUB3 complex plays a role in the inhibition of APC/C when spindle-assembly checkpoint is activated and inhibits the ubiquitin ligase activity of APC/C by phosphorylating its activator CDC20. This complex can also phosphorylate MAD1L1. Kinase activity is essential for inhibition of APC/CCDC20 and for chromosome alignment but does not play a major role in the spindle-assembly checkpoint activity. Mediates cell death in response to chromosome missegregation and acts to suppress spontaneous tumorigenesis.
Synonyms: hBUB1; BUB1L; BUB1A; MCPH30
Tractability: Small molecule: a structure with a bound ligand is known; a high-quality ligand is known; it has a binding pocket of medium quality; it belongs to a druggable protein family. PROTAC: it is named in the literature on targeted protein degradation; UniProt records ubiquitination sites on it; ubiquitination databases record sites on it; a small molecule that binds it is known.
Target class: Kinase; Enzyme; Protein Kinase
Chemical probes: BAY 1816032 (high quality)
Gene: Protein-coding gene on chromosome 2 (110,636,333 to 110,678,078, reverse strand). Ensembl gene ENSG00000169679.
Subcellular location: Nucleus; Chromosome, centromere, kinetochore
Subcellular location (Human Protein Atlas): Nucleoplasm; Cytosol
Pathways (Reactome):
Cell Cycle: Amplification of signal from unattached kinetochores via a MAD2 inhibitory signal; EML4 and NUDC in mitotic spindle formation; Mitotic Prometaphase; Resolution of Sister Chromatid Cohesion; Separation of Sister Chromatids
Signal Transduction: RHO GTPases Activate Formins
Gene Ontology:
Molecular function: histone H2A kinase activity; protein binding; protein kinase activity; protein serine/threonine kinase activity; ATP binding; protein serine kinase activity
Biological process: mitotic spindle assembly checkpoint signaling; positive regulation of maintenance of mitotic sister chromatid cohesion, centromeric; regulation of chromosome segregation; regulation of sister chromatid cohesion; meiotic sister chromatid cohesion, centromeric; chromatin remodeling
Cellular component: kinetochore; membrane; nucleoplasm; outer kinetochore; cytosol; nucleus
Genetic constraint (gnomAD): Loss-of-function variants: 70 observed, 117.5 expected, observed/expected ratio (o/e) 0.6, 90% interval 0.49 to 0.73. The upper end of that interval is the gene's LOEUF score, 0.73, which puts it in group 2 of 6, group 1 being the genes least tolerant of losing a copy. Missense variants: 1,066 observed, 1,207.7 expected, observed/expected ratio (o/e) 0.88, 90% interval 0.84 to 0.93. Synonymous variants: 373 observed, 410.63 expected, observed/expected ratio (o/e) 0.91, 90% interval 0.83 to 0.99.
Gene-disease validity (ClinGen):
ClinGen rates the evidence that BUB1 causes each of these diseases.
colorectal cancer (autosomal dominant): Limited. A primary or metastatic malignant neoplasm that affects the colon or rectum.
Homologues: Orthologues: chimpanzee BUB1 (97% identical), macaque BUB1 (96% identical), dog BUB1 (83% identical), pig BUB1 (82% identical), rabbit BUB1 (80% identical), guinea pig BUB1 (74% identical), mouse Bub1 (72% identical), rat Bub1 (72% identical), tropical clawed frog bub1 (46% identical), zebrafish bub1 (37% identical), Drosophila melanogaster Bub1 (20% identical), Drosophila melanogaster BubR1 (19% identical), and 2 more. Paralogues in human: BUB1B (21% identical).
Diseases named in the same sentence as BUB1 in open-access papers:
BUB1 is named in the same sentence as 131 diseases in open-access papers, as found by Europe PMC text mining. Sharing a sentence is not in itself a finding about the gene and the disease. The quoted sentences say what the papers report.
breast carcinoma (77 papers, 2006 to 2025). "A signature performed by four of these hub nodes (CDK1, PCNA, EZH2, and BUB1) was associated with relapse events in untreated luminal breast cancer patients." (PMID 38831458, 2024). "BUB1 has been widely reported to be associated with tumorigenesis in various cancer types including gastric cancer, breast cancer, and pancreatic ductal adenocarcinoma." (PMID 35769782, 2022). "High Expression of BUB1 has previously been reported to be linked with poorer prognosis and increased malignancy in lymphoma, prostate, gastric, and breast cancer." (PMID 36217480, 2022). "It was also found that overexpression of BUB1 was tightly associated with the development and progression of several human cancers, including breast cancer, prostate cancer, and hepatocellular carcinomas, as well as lymphoma and ovarian cancer." (PMID 34852826, 2021). "Aberrant expression and mutations in BUB1 are associated with aneuploidy and several types of cancer, including breast cancer and pancreatic ductal adenocarcinoma." (PMID 32269624, 2020). "In endometrial carcinoma and low-grade breast cancer high frequency of BUB1 is associated with a good prognosis while in invasive breast cancers and ovarian cancer BUB1 is associated with a poor prognosis." (PMID 29100315, 2017). "Overexpression of MAD2L1 and BUB1, candidate hub genes in our study, has previously been associated with high grade breast tumors and poor survival of breast cancer patients." (PMID 29088818, 2017). "Associations of MAD2L1 and BUB1 expression with clinical and molecular characteristics of breast cancer." (PMID 26287798, 2015). "We and others found high expression of MAD2L1 and BUB1 in breast cancer and their associations with unfavorable prognosis." (PMID 26287798, 2015). "Our investigation showed that high MAD2L1 or BUB1 expression was associated with poor prognosis of breast cancer, and moreover in vitro suppression of their expression resulted in reduced cell proliferation and less aggressive cell behavior." (PMID 26287798, 2015). "BUB1 has been implicated as a stem cell regulator in breast cancer." (PMID 40076867, 2025). "In this study, we further examined the clinical significance of a four-gene signature (comprising CDK1, PCNA, EZH2, and BUB1) that may be associated with relapse events in untreated luminal breast cancer patients." (PMID 38831458, 2024). "Although the mechanisms of action are not fully understood and still controversial, different studies correlated BUB1 expression (and limitedly BUB1 mutations) with poor prognosis in several cancers, including breast cancer, glioma, prostate cancer, and salivary gland tumours." (PMID 38396175, 2024). "BUB1 is overexpressed in breast cancer and is associated with poor clinical prognosis." (PMID 33644115, 2021). "Overexpression of Bub1 in breast cancer is associated with a poor clinical prognosis." (PMID 32983988, 2020). "Loss of BUB1 mitotic checkpoint serine/threonine kinase (BUB1) could reduce cancer stem cell potential of breast cancer cell line." (PMID 30175120, 2018). "In low grade breast cancer and endometrial cancer frequent BUB1 expression was seen in cancers with a favorable course, whereas in ovarian and invasive breast cancer, frequent expression of BUB1 was associated with a poor prognosis." (PMID 29100315, 2017). "Overexpression of BUB1 was linked with poor outcomes in breast cancer patients." (PMID 28427189, 2017). "We further investigated the associations of MAD2L1 and BUB1 expression with breast cancer survival." (PMID 26287798, 2015). "In endometrial carcinoma, low-grade breast cancer, and gastric adenocarcinoma, high expression levels of BUB1 were associated with a good prognosis, whereas in invasive breast cancer and ovarian cancer, high expression of BUB1 was associated with an unfavorable prognosis." (PMID 32269624, 2020).
breast carcinoma (continued). "Elevated BUB1 expression correlates with aggressive phenotypes and unfavorable prognosis in various cancers, such as pancreatic ductal adenocarcinoma, breast cancer, glioblastoma, and papillary thyroid cancer." (PMID 40180891, 2025). "BUB1 expression also shows promise as a predictive biomarker for immunotherapy response and clinical outcomes in breast cancer." (PMID 41208974, 2025). "Beyond these insights, BUB1 loss impaired migration and invasion, consistent with reports linking BUB1 to TGF-β signaling, cancer stemness, and EMT axis in lung and breast cancer cells." (PMID 40180891, 2025). "BUB1 expression is also much higher in breast cancer cell lines with basal-like characteristics and in cell lines with increased metastatic potential." (PMID 38863037, 2024). "BUB1 transcripts are significantly higher in breast cancer cell lines and in high-grade primary breast cancer tissues compared to normal mammary epithelial cells, or in normal breast tissues." (PMID 38863037, 2024). "Our study showed that BUB1 is overexpressed (differential mRNA levels) in breast cancer with the highest expression in TNBC." (PMID 38863037, 2024). "Accordingly, combinatorial treatment with ATR inhibitors showed synergy with BUB1 inhibition in breast cancer cell lines with functional ATM activity." (PMID 38396175, 2024). "Effect of siRNA-mediated BUB1 depletion on radiosensitization was measured in all the selected breast cancer cell lines." (PMID 38863037, 2024). "High expression of BUB1 and BUB3 in low-grade breast cancers was associated with longer overall survival." (PMID 36787437, 2023). "BUB1, a mitotic checkpoint serine/threonine kinase, serves an important role in the establishment of mitotic spindle checkpoint in breast cancer cells." (PMID 35627287, 2022). "BUB1 expression is correlated with a poor clinical prognosis in patients with breast cancer and, in general, it has the potential to improve the prediction of breast cancer prognosis." (PMID 36699355, 2022). "The expression of BUB1 was found to be upregulated in basal-like breast cancer, and BUB1 was required for maintaining cancer stem cell renewal in breast cancer cell lines." (PMID 34852826, 2021). "The other important gene and related protein is BUB1, whose expression is negatively correlated with breast cancer prognosis." (PMID 33452359, 2021). "Depletion of BUB1 in lung adenocarcinoma and breast cancer results in the abrogation of downstream effectors of phosphorylated PI3K/Akt and ERK, thereby leading to the suppression of cell proliferation, migration and invasion." (PMID 34337852, 2021). "BUB1 (budding uninhibited by benzimidazole 1) is a mitotic checkpoint protein that is overexpressed in various types of cancer, including breast cancer, gastric cancer, pancreatic cancer and so on." (PMID 34820170, 2021). "The abnormal expression of BUB1 is related to the occurrence and development of a variety of tumors, and it is also involved in the biological behavior of cancer stem cells such as breast cancer." (PMID 34696748, 2021). "We previously demonstrated that forced downregulation of miR-10b-3p in breast cancer perturbed BUB1, PLK1, and CCNA2 expression, hence accelerated tumor progression." (PMID 33230261, 2021). "To date, several studies have demonstrated that BUB1 is significantly upregulated in various types of cancer, such as breast cancer, pancreatic ductal adenocarcinoma, prostate and gastric cancer, and is associated with unfavorable outcomes." (PMID 32269624, 2020). "Here, for the first time,we are reporting downregulation of BUB1 expressionin breast cancer cells following overexpression of miR302/367 cluster." (PMID 31376326, 2020). "The function of BUB1 as oncogene or tumor suppressor gene has been observed in various types of cancer, including breast cancer, pancreatic ductal adenocarcinoma, prostate and gastric cancer." (PMID 32269624, 2020).
breast carcinoma (continued). "The high expression of BUB1 was observed in gastric carcinomas, breast cancer and have been reported to be involved in cancer cell differentiation." (PMID 29297280, 2017). "BUB1 has important roles in the proliferation or progression of breast cancer, and the nuclear BUB1 immunohistochemical status is considered to be an influential prognostic factor in human breast cancer patients." (PMID 27454576, 2016). "We used shRNAs targeting Bub1 (shBub1) to investigate the roles of Bub1 in breast cancer development and therapy." (PMID 26522589, 2015). "IAK-1/Aurora A, Bub1, BubR1 and Mps1 aneuploid kinase levels were upregulated in breast cancer spheres when compared to HMEC spheres." (PMID 26608463, 2015). "Taken together with the xenograft assay results, these results suggest that depleting Bub1 reduced the CSC potential of breast cancer cell lines." (PMID 26522589, 2015). "We identified that depleting Bub1 in the MDA-MB-231 a breast cancer cell line prevents generation of xenografts in immunocompromised mice due to reduced CSC potential in Bub1-depleted cells and resulted in radiosensitization." (PMID 26522589, 2015). "In summary, our study confirmed the prognostic value of two key mitotic checkpoint genes MAD2L1 and BUB1, which have been included in multiple gene expression signatures for breast cancer prognosis." (PMID 26287798, 2015). "We identified that depleting Bub1 using shRNAs reduces cancer stem cell potential of the MDA-MB-231 breast cancer cell line, resulting in inhibited formation of xenografts in immunocompromised mice." (PMID 26522589, 2015). "Using the gene expression data from our microarray analysis of breast cancer, we examined the associations of MAD2L1 and BUB1 expression with tumor features and disease outcomes." (PMID 26287798, 2015). "The mRNA and protein levels of CDC20 and BUB1 have been shown to be significantly higher in breast cancer cell lines and in high-grade primary breast cancer tissues." (PMID 25385471, 2015). "In our study of microarray expression data from 203 breast cancer patients, we analyzed the genes present in multiple signatures, and found three genes (MAD2L1, PTTG1 and BUB1) significantly associated with disease-free or overall survival." (PMID 26287798, 2015). "The overexpression of BUB1 or CDC20 induces misregulation of APC, and is associated with the chromosomal instability and poor outcomes in breast cancer patients." (PMID 24758163, 2014). "This was exemplified by its overexpression of 'breast cancer proliferation signatures', including BUB1, Polo-like kinase, and numerous cyclins, which are also upregulated in tumours compared with primary normal epithelium (and references therein)." (PMID 18588681, 2008). "In addition, BUB1 expression was proposed as a predictor of response to immunotherapy in breast cancer tumors." (PMID 40723917, 2025). "Based on these observations, we hypothesize that breast cancer cell lines that express high BUB1 would be radiosensitized by BAY1816032 while the cell lines that express low to moderate BUB1 would not." (PMID 38863037, 2024). "BUB1 is overexpressed in most human solid cancers, including breast cancer." (PMID 38927028, 2024). "High BUB1 expression (transcript) correlates with extremely poor outcome in breast cancer." (PMID 38863037, 2024). "Dysregulation of BUB1/3, the key mediators of spindle assembly checkpoints, has been reported to result in the incidence and development of various types of cancers, such as stomach cancer, leukemia, liver cancer, and breast cancer." (PMID 36787437, 2023). "BUB1 is related with the most cancer stem cell attainable in breast cancer." (PMID 36213825, 2022). "The expression of key markers associated with proliferation (MKI67, PCNA, CCNB1, MYBL2, BUB1, CCND1), apoptosis (BCL2, CASP7, CASP8, CASP9, CASP3, BAX, APAF1), differentiation (CDH1, CD24, EPCAM, ESR1, NGFR, RUNX1), and breast cancer stemness (CD44, ITGA6, DNER, ALDH1A3, ABCG2, PROCR) was assessed." (PMID 35183258, 2022).